CRP (C-reactive protein)
Diseases named in the same sentence as CRP in open-access papers (continued):
Sharing a sentence is not in itself a finding about the gene and the disease.
abscess (continued). "The WBC count, CRP level, and ESR of patients with this type of abscess usually increase to varying degrees, whereas the procalcitonin level likely remains in the normal range or increases only slightly." (PMID 39185468, 2024). "Among these patients, high CRP, high WBC, larger abscesses, and the presence of RPE, ME, VSE, and SLSE predicted extraoral surgery, among which ME was the strongest predictor at the multivariate level." (PMID 36617619, 2023). "The abscess size at admission (25.85 ± 16.68 cm2 vs. 26.71 ± 13.99 cm2; P = 0.744), WBC count (16.93 ± 6.06 × 109/L vs.18.72 ± 6.11 × 109/L; P = 0.095), and CRP level (62.14 ± 29.35 vs. 73.67 ± 50.28; P = 0.133) were also similar between the two groups." (PMID 37063672, 2023). "In a multivariate analysis, C-reactive protein (CRP) levels, RPE, and maximal abscess diameter were independent predictors of the need for ICU treatment, and CRP, ME, and maximal abscess diameter were independent predictors of LOS." (PMID 34331114, 2022). "Despite these limitations, dichotomization by median LOS did identify elevated CRP as well as the imaging findings of RUQ FF and abscess on presentation as predictive of a worse outcome." (PMID 35463908, 2022). "The patient had symptoms of abscess compression before surgery, and inflammatory indicators such as erythrocyte sedimentation rate (ESR), C-reactive protein (CRP), and procalcitonin (PCT) were significantly elevated." (PMID 35372474, 2022). "In 307 patients with MRI edema patterns and clinical data available for analysis, the need for ICU treatment was predicted by CRP (p = 0.015), RPE (p = 0.004), and maximal abscess diameter (p = 0.006) (model 3)." (PMID 34331114, 2022). "In these studies, despite the relationship between abscess formation and high WBC, CRP, and NLR values, the sensitivity and specificity ratio of NLR in the BA group was determined to be lower." (PMID 33083171, 2020). "Inflammatory markers in the blood, such as C-reactive protein (CRP), indicate systemic inflammation in severely active IBD and disease complications such as abscess formation and bowel perforation." (PMID 31756948, 2019). "Based on the significant predictors and their regression coefficients, the following risk score formula was derived: 3 *RPE (present/absent) + 2 * (CRP>171.5 mg/L, yes/no) + 2 * (abscess diameter >39.5 mm, yes/no)." (PMID 40236980, 2025). "However, both CRP (p = 0.045) and PCT (p = 0.005) medians were significantly higher in perforation/abscess compared to gangrenous appendicitis." (PMID 40067493, 2025). "In addition to clinical symptoms and signs, laboratory parameters such as C-reactive protein (CRP), white blood cell (WBC) count, neutrophil count, lymphocyte count, and monocyte count are often used to assess the severity of an abscess." (PMID 39410567, 2024). "Although prior research has established CRP as a key inflammatory marker in assessing the severity of infections, including odontogenic abscesses, our findings suggest that the AISI provides superior predictive value for abscess severity." (PMID 39410567, 2024). "If a severe abscess did not occur at a critical site and invade the esophagus, esophageal perforation almost never happened, even with a high CRP level or involvement of multiple spaces." (PMID 35624431, 2022). "Overall, the patients with RPE and ME had higher incidence of markers consistent with more severe disease, including higher incidence of ICU treatment, larger abscesses, higher CRP, and longer LOS, than those without." (PMID 34331114, 2022). "The absence of abscesses on CT, at a younger age, and a raised C-reactive protein (CRP) are helpful to differentiate (LKD) from BCL." (PMID 35743997, 2022). "This highlights the significance of imaging and suggests that low CRP does not exclude an abscess in children." (PMID 35184213, 2022).
abscess (continued). "Regression analysis indicated that the presence of abscess (OR = 3.60; 95%CI = 1.36–9.48; p = 0.01) and presence of RUQ FF on initial imaging (OR = 2.68, 95%CI = 1.05–6.79; p = 0.038) and CRP > 12 (OR = 2.84; 95%CI = 1.10–7.32; p = 0.031) were independently associated with a longer LOS." (PMID 35463908, 2022). "If severe abscess did not occur at a critical site and result in a compromised airway, tracheostomy was not required (even with a high CRP level)." (PMID 34573878, 2021). "Preoperative CRP or WBC did not correlate with abscess formation or any other outcome marker measured." (PMID 33163468, 2020). "In cases of two potential equal matches for the abscess size, CRP level functioned as a secondary matching criterion (without any maximum threshold for difference)." (PMID 31320921, 2019). "C-reactive protein (CRP) level on admission and Charlson Comorbidity Index were higher, and the use of glucocorticoid medication was more frequent among patients with larger abscesses." (PMID 31320921, 2019). "At Week four, all participants will undergo abdominal imaging and be assessed for clinical response (CRP < 20 mg/l, absence of fever, plus scan showing that the maximal diameter of the abscess has reduced)." (PMID 24176222, 2013). "CRP did not retain significance in our multivariable logistic regression model, likely reflecting its role as a nonspecific acute-phase reactant elevated in both abscess and cellulitis cases." (PMID 41153226, 2025). "When comparing the analysis of the AISI score (SE = 82.93, SP = 81.63, AUC = 0.90, Y = 0.65, p = 0.0001) and CRP levels (SE = 70.73, SP = 72.45, AUC = 0.78, Y = 0.43, p = 0.0001), it is clear that AISI score has significant prognostic value in predicting the seriousness of an abscess." (PMID 39410567, 2024). "In addition, because of changes in the electronic medical records system, much data were not recorded consecutively, such as body temperature, abscess size, body mass index, white blood cell count, C-reactive protein, procalcitonin, and pus cultures." (PMID 35601425, 2022). "However, if severe abscesses did not occur at a critical site, a high CRP level did not necessarily predict the concurrence of DNI and LS." (PMID 35453976, 2022). "Several studies indicated that CRP is a useful negative predictive test for the development of anastomotic leakage and in detecting abscess formation after LSG and colorectal surgery with remarkably higher sensitivity and specificity than WBC or neutrophil count." (PMID 36167572, 2022). "Monitoring systemic inflammatory markers, such as C-reactive protein (CRP), and follow-up with magnetic resonance imaging (MRI) are mandatory to assess the adequate response to therapy, clarify the presence of abscess to drain, and identify spinal instability that could benefit from surgery." (PMID 33321967, 2020). "Our results suggest that the new, easy-to-measure AISI score is an extremely useful tool for the clinical assessment of abscess severity, outperforming not only the SII but also other non-inflammatory scores and CRP." (PMID 39410567, 2024). "Indeed, the present patient had no fever or serum WBC elevation and only showed slight serum CRP elevation, suggesting that the absence of systemic inflammation and infection and the formation of the rectal fistula may have avoided worsening of the infection through drainage of the abscess." (PMID 39749292, 2025). "When diagnosing abscesses and other soft tissue infections, the white blood cell count and inflammatory markers such as the Erythrocyte Sedimentation Rate (ESR) and C-Reactive Protein (CRP) are generally considered to be nonspecific." (PMID 40336692, 2025).
liver disease (166 papers, 2005 to 2026). "We aim to explore if systemic low-grade inflammation, measured by plasma high-sensitivity C-reactive protein (hs-CRP), is also linked to steatotic liver disease in adolescents." (PMID 41745591, 2026). "In contrast, heart rate, history of peptic ulcer, history of liver disease, and CRP showed a positive association." (PMID 41585275, 2025). "In HCC patients’ liver function is often impaired due to an associated underlying liver disease (e.g. hepatitis, nonalcoholic fatty liver disease) and CRP and albumin are primarily synthesized by hepatocytes." (PMID 41142780, 2025). "Whereas the gene CRP, which encodes the C-reactive protein, a marker of chronic inflammation that has been associated with liver diseases, was upregulated in aged liver." (PMID 37378670, 2024). "After excluding patients with pre-existing liver disease, all associations remained except those with acute CRP and steroid treatment." (PMID 37748493, 2023). "While ICU admission and albumin were recognized as predictors of short-term mortality, we identified some risk factors related to CDI severity, such as leukocytes, CRP and Atlas score, and to the liver disease—mainly Child–Pugh score and MELD." (PMID 34204307, 2021). "An association between CRP expression levels and liver disease, including nonalcoholic fatty liver disease (NAFLD), fibrosis, and hepatitis has been reported." (PMID 33005688, 2020). "Several studies have been performed on the association of CRP with the severity of inflammation in liver disease, such as fatty liver and chronic hepatitis C (CHC)." (PMID 32774512, 2020). "In this study, we included the inflammatory parameters CRP and leukocytes, since high levels of reactive oxygen species, which are associated with oxidative stress and inflammatory processes, are seen in hepatic disease." (PMID 30474548, 2018). "The analysis identified a history of peptic ulcer, hemoglobin (Hb), platelet count (PLT), albumin (ALB), heart rate, systolic blood pressure (SBP), liver disease, and CRP as significant independent risk factors for 1-year rebleeding in patients with acute upper gastrointestinal bleeding." (PMID 41585275, 2025). "Among the clinical variables examined, the severity of liver disease and the coexistence of liver cancer were associated with SA ≤35 g/L; among the laboratory variables SA values ≤ 35g/L were associated with elevated hs-CRP." (PMID 39165413, 2024). "Therefore, age, deceased donor, liver disease, eGFR at baseline and admission, glycemic control before admission, CRP, and LDH were associated with the need for HD." (PMID 36366507, 2022). "However, parameters of bacterial translocation and systemic inflammation—except for CRP levels—were similar in patients with low-risk versus high-risk portal hypertension." (PMID 33000389, 2020). "Distinct plasma-mediated inflammatory responses, as defined by our laboratory assay and changes in WCC and CRP from baseline during the first week of hospitalization, were associated with organ dysfunction and death in albumin-treated advanced liver disease patients." (PMID 31446184, 2020). "Possible explanations for these findings, since they have also been shown in other studies, are related to the involvement of inflammatory cytokines in the early stage of many liver diseases, supporting the association of heavy alcohol intake and increased levels of IL-6 and CRP." (PMID 31071114, 2019). "Moreover, higher CRP levels could be associated with underlying liver disease, which is common among patients with alcoholic etiology of AP." (PMID 40002586, 2025). "However, whether monomeric forms of CRP and mCRP autoantibodies are associated with the severity and prognosis of liver disease remains unknown from existing studies." (PMID 38895111, 2024). "A new model was developed based on heart rate, blood pressure, hemoglobin, history of peptic ulcer, comorbid liver disease, albumin, platelet count, and CRP." (PMID 41585275, 2025).
liver disease (continued). "CRP is a key marker of inflammation, while the albumin level decreases not only in inflammatory conditions but also due to factors such as liver diseases, kidney diseases, and malnutrition." (PMID 40087374, 2025). "This process selected eight predictors: heart rate, systolic blood pressure, hemoglobin, history of peptic ulcer, history of liver disease, platelet count, albumin, and CRP." (PMID 41585275, 2025). "While prior reports have suggested CRP elevation in advanced liver disease stages such as cirrhosis or HCC, our findings indicate that CRP is not a useful biomarker of viral activity in the early phase." (PMID 41012636, 2025). "By using AST-stratified Cox models in conjunction with CRP mediation analyses, this study advances the mechanistic understanding of the relationship between myopia and liver disease and identifies systemic inflammation as a potential biological pathway." (PMID 40869686, 2025). "For example, evidence indicates that poor oral health is associated with elevated levels of inflammatory markers, such as C-reactive protein (CRP), which are known to be linked to various liver diseases." (PMID 40270511, 2025). "When adjusting for age, sex, smoking, alcohol, liver disease, baseline C-reactive protein, body mass index, and renal function, 277 (66%) of these 418 outcomes persisted at this threshold." (PMID 37456363, 2023). "CRP is an acute phase reactant, which elevates in infectious and non-infectious conditions, including rheumatologic diseases, kidney, or liver diseases." (PMID 35626186, 2022). "It has been shown that changes in the levels of biomarkers such as CRP, lymphocytes, neutrophils, and cytokines such as IL-6 can, in turn, lead to liver disorders." (PMID 36531832, 2022). "CRP is produced in the liver and its levels are markedly reduced in liver diseases and following liver surgeries; thus, further limiting its use as an early marker for predicting the outcomes following liver surgeries." (PMID 35706741, 2022). "C-reactive protein is a marker of systemic inflammation, where it is found to be a predictor of mortality in patients with liver disease." (PMID 34980174, 2022). "Regarding 6-week mortality, our analysis showed that it correlated with FABP2, albumin, CRP levels, severity of liver disease, and the presence of severe cirrhosis-related complications, including portal vein thrombosis and hepatocellular carcinoma." (PMID 35308545, 2022). "Our findings support already published data, which explore the correlation between C-reactive protein, portal hypertension and mortality." (PMID 35625755, 2022). "After PS matching, most of the patients' characteristics were found to be comparable between the two groups, except that patients who received iNO had a lower baseline C-reactive protein (CRP) and higher liver disease as comorbid conditions." (PMID 36192801, 2022). "The absolute neutrophil count as well as the CRP levels were reduced after diagnosis of portal hypertension." (PMID 35821451, 2022). "The predictive power on mortality of low albumin levels in an unselected acutely admitted medical population (5894 adult patients) found an OR of 3.91 when adjusting for CRP, liver disease, renal disease, cancer and rheumatologic disease." (PMID 33956870, 2021). "Secondly, confounding factors that would obscure changes in and affect CRP levels, such as patients with inflammatory arthritis, concurrent infection of other organs, or renal or liver diseases, were excluded from the final analysis." (PMID 34856956, 2021). "Intriguingly, in a most recent study, both CRP and GSH, well known as an antioxidant, have been demonstrated to exert synergistic effects in the association of severe hepatic diseases." (PMID 35047538, 2021). "In any case, the interpretation of the results should consider C-reactive protein levels, especially in patients with inflammatory processes associated with COPD and liver disease." (PMID 34768650, 2021).
liver disease (continued). "Patients showed not only higher levels of D-dimer but also higher levels of CRP and creatinine, probably due to increased vascular permeability, kidney, or liver disease." (PMID 33968298, 2021). "On admission, the levels of CRP and the production of the cytokines IL-6, IL-10, and M-CSF were significantly elevated in patients with a liver disorder." (PMID 32903864, 2020). "The biochemical data related to nutritional status, including total cholesterol, serum albumin, transferrin, prealbumin, and CRP, are influenced by medical conditions, including malignancy, liver disease, infection, stress, and critical illness." (PMID 32053672, 2020). "In our study, VWF levels were independently and positively associated with decompensated disease, severity of portal hypertension (HVPG), indicators of hepatic dysfunction, liver injury/hepatic inflammation (AST/GGT) and systemic inflammation (CRP)." (PMID 32052552, 2020). "Further, C-reactive protein levels were much higher in the hepatic disorder group, with significantly higher concentrations of IL-6, IL-10, and M-CSF." (PMID 32903864, 2020). "The median level of C-reactive protein (CRP) was higher in the hepatic disorder group, with a significantly higher concentration of IL-6, IL-10, and M-CSF." (PMID 32903864, 2020). "Aetiology of liver disease, age, nutritional status and inflammation (CRP levels) are further explanatory variables." (PMID 31943691, 2020). "Few studies have been performed to examine the value of the CRP in assessing the conditions of liver function damage among HBV-related liver diseases." (PMID 32774512, 2020). "In this investigation we aimed to characterize not only the evolution of liver disease by liver enzymes, CRP, abdominal ultrasound but also its relation to the neurological status studied by Klockgether Ataxia Score (KAS) in a large cohort of A-T patients." (PMID 31788461, 2019). "After further adjustment to account for liver disease (serum ferritin <15μg/L or <30μg/L in the presence of inflammation (CRP >5 mg/Land ALT >45 U/L), 40.2% (95% CI 37.5–43.0) women were classified as having ID." (PMID 30562390, 2018). "Multiple logistic regression analyses of the relationships between Clinically significant portal hypertension & sMR, CRP, GEC, and MELD-score." (PMID 29236785, 2017). "Positive associations of CRP, IL-6 and LBP have been reported before by others; however, in these studies, patients suffered from severe liver disease e.g. cirrhosis with infection." (PMID 28880885, 2017). "Several studies in human patients with liver disease have examined the role of circulating biomarkers as adjunctive markers of systemic inflammation, such as LPS, procalcitonin and C reactive protein." (PMID 26808672, 2016). "Plasma HGF concentrations are higher not only in liver diseases but also in patients with acute infections (positively correlating with inflammatory parameters, including C-reactive protein)." (PMID 26448742, 2015). "Increasing concentrations of CRP have been observed in melioidosis patients and these increases have positively correlated with liver disease or dysfunction and poor clinical outcomes." (PMID 25503969, 2014). "The level of CRP tended to increase as liver disease progressed from Child-Pugh class A to C as well as tumor stage from I to IV." (PMID 23409924, 2013). "In our cohort, PV‐1 was associated with the severity of liver disease, that is, compensation/decompensation status, albumin, platelet count, INR and bilirubin, but also with inflammatory markers such as WBC count and the acute phase proteins CRP and LBP." (PMID 40317887, 2025). "The final logistic regression model was constructed as follows: Logit (P) = −0.812 + 0.036 × (Heart Rate) −0.032 × (Systolic Blood Pressure) + 2.989 × (History of Peptic Ulcer) + 2.213 × (Presence of Liver Disease) + 0.114 × (Albumin) −0.048 × (Hemoglobin) −0.011 × (Platelet Count) + 0.122 × (CRP)." (PMID 41585275, 2025).